ENSG00000200150
Synonyms: LOC124903418
Gene: Small nucleolar RNA gene on chromosome 14 (100,956,240 to 100,956,312, forward strand). Ensembl gene ENSG00000200150.
Gene Ontology:
Biological process: RNA processing
Cellular component: nucleolus
Homologues: Paralogues in human: SNORD114-15 (67% identical), SNORD114-21 (66% identical), SNORD114-3 (66% identical), SNORD114-13 (64% identical), SNORD114-4 (64% identical), SNORD114-14 (63% identical), SNORD114-23 (63% identical), SNORD114-5 (63% identical), SNORD114-6 (63% identical), SNORD114-12 (62% identical), SNORD114-25 (62% identical), SNORD114-28 (62% identical), and 27 more.